MAZ (MYC associated zinc finger protein)
Diseases named in the same sentence as MAZ in open-access papers (continued):
Sharing a sentence is not in itself a finding about the gene and the disease.
thyroid cancer (1 paper, 2023). "Myc‐associated zinc finger protein (MAZ) silence significantly inhibited cell viability, proliferation, migration, and invasion of thyroid cancer cells, whereas the inhibitory effect was reversed by TANK‐binding kinase 1 (TBK1) overexpression." (PMID 36988258, 2023). "In addition, Myc‐associated zinc finger protein (MAZ) was overexpressed in thyroid cancer and transcriptionally activated BK1." (PMID 36988258, 2023). "MAZ silencing markedly inhibited the proliferation and migration of thyroid cancer cells and reversed the effect of TBK1 overexpression." (PMID 36988258, 2023). "MAZ silencing inhibited tumor progress of thyroid cancer cells, whereas this inhibitory effect was reversed by TBK1 overexpression." (PMID 36988258, 2023). "MAZ silence reversed the effects of TBK1 overexpression on thyroid cancer progression." (PMID 36988258, 2023). "MAZ silencing markedly inhibited migration and invasion, and TBK1 overexpression reversed the inhibitory effect of MAZ silencing on thyroid cancer cells." (PMID 36988258, 2023). "Both MAZ and TBK1 silencing significantly decreased the viability and proliferation of thyroid cancer cells, whereas the inhibitory effect was not further enhanced by the cotransfection with MAZ siRNA and TBK1 siRNA." (PMID 36988258, 2023). "Silencing MAZ and TBK1 alone significantly inhibited the PI3K/Akt/mTOR pathway in thyroid cancer cells, whereas cotransfection with MAZ siRNA and TBK1 siRNA did not strengthen the inhibitory effect of MAZ RNA or TBK1 siRNA on the PI3K/Akt/mTOR pathway." (PMID 36988258, 2023).
tumor (44 papers, 2008 to 2025). "This study is the first to systematically investigate the relationship between myc‐associated zinc‐finger protein (MAZ) isoforms and tumor metastasis, as well as the clinical and prognostic value in GC." (PMID 40411278, 2025). "MAZ promotes tumor-associated angiogenesis by controlling genes like VEGF; its repression can be induced by factors such as oxidative stress and epigenetic changes, sustaining tumor growth and blood supply through pathways like STAT3 signaling." (PMID 41155227, 2025). "MYC associated zinc finger protein (MAZ) plays a key role in regulation of gene expression and tumor development." (PMID 27861158, 2016). "CircCUX1 interacts with EWS RNA-binding protein 1 (EWSR1) to enhance its binding with MYC-associated zinc finger protein (MAZ), leading to the increased transactivation of MAZ and the subsequent transcriptional changes in genes linked to tumor progression, including CUX1." (PMID 39452835, 2024). "We demonstrated that SETD1B, driven by MAZ, enhances stem characteristics by promoting anchorage-independence, cellular adhesion, tumor sphere formation, and growth via the surface glycoprotein CD24." (PMID 40860182, 2025). "To evaluate the MAZ expression in pan‐cancer, we first analyzed MAZ mRNA expression between tumor and adjacent normal tissues via the TIMER database." (PMID 40411278, 2025). "Substantial evidences have demonstrated that abnormal expression levels of MAZ is involved in tumor growth and inflammatory progression processes, which has been proposed as an important influencing factor in the occurrence and development of cancer." (PMID 41444950, 2025). "In TNBC, transcription factor MAZ was reported to directly regulate multiple assumed tumor-promoting genes, such as SIPL1 and BCKDK to accelerate progression of TNBC." (PMID 41444950, 2025). "All these contradictory findings suggest that the effect of MAZ on tumor metastasis is more complex than previously thought." (PMID 40411278, 2025). "Transcriptome data from clinical samples revealed that expression of both MAZ and RACGAP1 was increased in BRCA tumor tissue than that in normal tissue, and there was significant positive correlation between MAZ and RACGAP1." (PMID 41444950, 2025). "For instance, FOXA1, NWD1 and MAZ have been shown to promote tumor progression by modulation of androgen receptor expression and are frequently linked with poor prognosis." (PMID 36818049, 2023). "MAZ, a transcription factor, has been shown to exhibit aberrant expression in various tumor types, playing a role in the regulation of tumor cell proliferation, migration, apoptosis, and autophagy." (PMID 38086789, 2023). "Our previous study found that MAZ was increased in ccRCC and the upregulation of MAZ facilitated tumor progression." (PMID 36890610, 2023). "TME analysis by using “estimate” stated that the higher expression level of MAZ was related to higher tumor purity and a lower percentage of immune cells and stromal cells, which provided additional proof of its prognostic value." (PMID 35988113, 2022). "Circ-CUX1 binds to EWSR1 and promotes interaction with MAZ, leading to transactivation of MAZ and transcriptional alterations of CUX1 and other genes associated with tumor progression." (PMID 35116058, 2021). "A growing body of experimental and clinical data indicates that MAZ plays a key role in tumor differentiation, EMT, invasion and metastasis." (PMID 32268297, 2020). "MAZ is an oncogenic transcription factor associated with multiple cancers; while MEF2A is tumor repressive and its mutation is associated with tumorigenesis." (PMID 32483180, 2020).
tumor (continued). "Circ-CUX1 can directly interact with EWSR1 and facilitate EWSR1-MAZ interaction, resulting in transactivation of MAZ and transcriptional alteration of CUX1 and other genes associated with tumor progression." (PMID 32547943, 2020). "Isolation of the MAZ protein using a stable K-Ras promoter analog prevents MAZ from activating K-Ras transcription and delays tumor growth in mice." (PMID 32268297, 2020). "H&E staining of the tumors section from the tibias of inoculated mice showed that downregulating MAZ obviously remitted the tumor burden in bone." (PMID 31488180, 2019). "Multiple studies have revealed that MAZ plays an important role in the activation of RAS signalling by varying mechanisms in several tumor types." (PMID 31488180, 2019). "H&E staining of tumor sections from the tibias of inoculated mice showed that upregulation of MAZ significantly aggravated while downregulation of MAZ clearly reduced the tumor burden in bone." (PMID 31488180, 2019). "(C-F) Immunohistochemical (IHC) staining of MAZ, KRas and HRas protein expression in representative samples of tumor-bearing mice inoculated with vector (n = 10), MAZ (n = 10),scramble(n = 10) and sh-MAZ-1# (n = 10) cells." (PMID 31488180, 2019). "We detected the expression of ZEB1 and ZEB2 in the 75 pairs of HCC and adjacent non-tumor tissues that MAZ expression had been measured by IHC." (PMID 27861158, 2016). "Compared with adjacent non-tumor tissues, MAZ was significantly more highly expressed in 86.9% (20/23) of HCC tissues." (PMID 27861158, 2016). "Altered Prox1 mRNA expression is partly regulated by MAZ, and mutation of the prospero domain in HCC indicates an involvement for Prox1 during tumor progression." (PMID 18400094, 2008). "Additionally, MAZ is involved in tumor progression by directly binding to the promoter regions of target genes or synergizing with other transcription factors." (PMID 40411278, 2025). "MAZ was highly expressed in tumor tissues compared with adjacent normal tissues." (PMID 40411278, 2025). "PUF60 and MAZ together play a critical role in the regulation of tumor progression." (PMID 40411278, 2025). "To confirm whether PCGF6 is also involved in regulating hypomethylation of MAZ promoter in vivo, we tested the level of methylation in xenograft tumor tissue." (PMID 36890610, 2023). "In addition, the high expression of MAZ is also related to high tumor purity and immune infiltration." (PMID 35988113, 2022). "Furthermore, we found that MAZ was a core gene indicating the connection of tumor prognosis and AS events." (PMID 35988113, 2022). "The study suggested that the transactivation and transcriptional alteration of MAZ could modulate the process of aerobic glycolysis in tumor." (PMID 33439992, 2021). "Knockdown or ectopic expression of EWSR1 or MAZ rescued tumor cells from these changes." (PMID 31709724, 2019). "Mechanistically, transcription factor p110 CUX1, a proteolytic product of p200 CUX1, promotes expression of glycolytic genes, while circ‐CUX1 facilitates EWSR1‐mediated MAZ transactivation to alter expression of p200 CUX1 and other genes associated with tumor progression." (PMID 31709724, 2019). "Notably, circ‐CUX1 bound to RRM region of EWSR1, resulting in EWSR1‐mediated MAZ transactivation, suggesting the oncogenic roles of circ‐CUX1/EWSR1/MAZ axis in aerobic glycolysis and tumor progression." (PMID 31709724, 2019). "Interestingly, besides HBxΔ31 interacting with MAZ resulting in RhoGDIα down-regulation, over-expressed miR-151 can repress RhoGDIα expression and facilitate tumor cell migration and spreading in HCC." (PMID 27391153, 2016).
tumor (continued). "MAZ was initially described as a protein binding to a 16 bp region of the MYC promoter and has been implicated in transcriptional activation of target genes and regulation of tumor cell proliferation and apoptosis." (PMID 25749382, 2015). "For example, MAZ was reported to up-regulate the expression of BCKDK, a highly expressed gene in TNBC tumor tissues involving in promoting tumorigenesis." (PMID 41444950, 2025). "By contrast, in the Met group, TFs related to tumor angiogenesis, metastasis and EMT, such as XRCC4, MYC and MAZ showed elevated activity 23–25." (PMID 41413734, 2025). "MAZ, a member of the C2H2 transcription factor family, is involved in gene expression and tumor development." (PMID 40411278, 2025). "A similar mechanism is observed with MAZ, which, by activating VEGF and supporting angiogenesis, ensures that the tumor has a supply of nutrients and oxygen, providing an adaptive advantage, even though it is not a direct driver." (PMID 41155227, 2025). "Based on Oncomine database, we identified that expression of CCR1, CD3D, MAZ, PHLDA1, and RASD1 was higher in tumor than that in normal tissue at the pan-cancer level." (PMID 36092920, 2022). "The 5 genes (TTC39C, HSPBP1, MAZ, ANK3 and ZC3HAV1) where model AS events occurred were analyzed for the differential expression level between normal breast tissue and tumor tissue." (PMID 35988113, 2022). "For further prove the expression of MAZ in HCC, we performed immunohistochemical analysis (IHC) to detect MAZ protein in another 75 pairs of HCC and adjacent non-tumor tissue samples." (PMID 27861158, 2016). "In order to clarify the relationship between MAZ, ZEB1 and ZEB2 in HCC, we detected their expression in 75 pairs of HCC and adjacent non-tumor tissues." (PMID 27861158, 2016). "In order to investigate the relationship between MAZ and HCC, we firstly examined protein expression of MAZ in 23 pairs of HCC and adjacent non-tumor tissues by Western blot." (PMID 27861158, 2016). "Previous reports showed that full-length HBx can transcriptionally suppress a subset of important tumor-related genes through enhancing the promoters binding to transcription suppressors like E2F1, SMAD4, YY1 and MAZ." (PMID 27391153, 2016). "We found that MAZ was over-expressed in HCC tissues, and correlated with tumor diameter and distant metastasis." (PMID 27861158, 2016). "These target genes are known to participate in tumor progression, but the suggested regulatory roles of PAX4, BACH1, BACH2, MAZ and TAF8 in the process is new." (PMID 21682879, 2011). "We also showed that both PPARγ1 and MAZ are highly expressed in MCF-7 cells as compared to normal mammary epithelial cells (HMEC) and tumor-specific expression of PPARγ1 is MAZ dependent." (PMID 19061500, 2008). "Importantly, both condensation capacity and G4-binding affinity were indispensable for MAZ to promote HCC cell proliferation and tumor growth, suggesting the biologically relevance of our discovery." (PMID 38316778, 2024). "Generally consistent with in vitro data, only MAZ-WT and ΔZF5-FUS-IDR could promote tumor growth, while all other mutants virtually lost this ability, showing tumor growth comparable to vector control." (PMID 38316778, 2024). "MAZ is reported to be upregulated in ccRCC tissues and cells, and this increases ccRCC cell growth and tumor progression (data not shown)." (PMID 36890610, 2023). "In summary, these results suggest that AQP1 overexpression may enhance tumor progression by interacting with the transcriptional regulation networks governed by FOXO4, MAZ, and E2F TFs." (PMID 38057925, 2023). "In accordance with the result from Western blot, expression of MAZ was significantly higher in HCC tissues than in adjacent non-tumor tissues." (PMID 27861158, 2016).
tumor (continued). "Using EMSA, a significant binding was found to the MAZ-consensus site-containing the 5'-flanking sequences of the "Prox1-7902" transcript, in the cell nuclear extracts of HCC cell lines, of Mz-Cha2 cell line and of a HCC tumor sample." (PMID 18400094, 2008). "Overall, we demonstrated a regulatory mechanism that CCND1-G4 recruits MAZ and promotes molecular motility in MAZ condensates, which compartmentalize coactivators to activate CCND1 gene expression, and subsequently augment HCC cell proliferation and tumor progression." (PMID 38316778, 2024). "Furthermore, we found that the level of MAZ mRNA in ccRCC tissue was positively correlated with tumor size, but not with other clinicopathological factors, such as age, gender, and tumor grade." (PMID 34183010, 2021). "There was a significant correlation between MAZ expression with smoking, alcohol intake, tumor diameter and metastasis (P < 0.05), while there was no statistical correlation between MAZ with other clinicopathologic parameters of HCC patients, such as sex, age and HBV infection (P > 0.05)." (PMID 27861158, 2016). "In addition, therapeutic approaches aimed at disrupting key regulatory interactions, including those involving TAF1, MYC, MAZ, and other TFs such as KLF15 and ZNF281, may suppress tumor growth and modulate stress adaptation, thereby enabling more precise interventions against cancer." (PMID 41155227, 2025). "While many of the identified transcription factors were described as central to cancer development (including SMARCB1, MAZ, EZH1 and H2AFX), none had an established role in ES, likely due to the limited number of functional studies of this tumor type." (PMID 34359637, 2021).
cancer (35 papers, 2008 to 2025). A tumor composed of atypical neoplastic, often pleomorphic cells that invade other tissues. "Myc-associated zinc finger protein (MAZ) is a widely expressed TF and has a crucial role in regulating gene transcription related to cancer progression, including proliferation, apoptosis, and angiogenesis." (PMID 41155227, 2025). "As a transcription factor, the upregulation of MAZ has been extensively implicated in tumorigenesis, progression, and metastasis in various types of cancer." (PMID 31488180, 2019). "Similarly, we observed RNA-specific MSI events in cancer-related genes such as MAZ (MYC Associated Zinc finger gene), INO80E (DNA-repair related gene), and RPL genes (ribosome-related genes)." (PMID 39210504, 2024). "We further explored the relationship between MAZ expression level and prognosis in 13 malignant tumors with up‐regulation of MAZ in both the TIMER and GEPIA databases." (PMID 40411278, 2025). "We detected the expression of the MAZ gene by immunohistochemistry (IHC) in our archived GC tissue microarray and found that MAZ was expressed mainly in the nucleus of cancer cells." (PMID 40411278, 2025). "MAZ was recognized to play a pro-cancer role by exerting the transcriptional regulation effects upon the many genes related to various cellular processes, including the regulation of cell proliferation, EMT, angiogenesis, autophagy, etc.." (PMID 38315284, 2024). "MAZ is highly expressed in many human tumors and promotes cancer development, progression, and metastasis via transcriptional activation of multiple downstream target genes." (PMID 37398932, 2023). "MAZ is involved in the progression and metastasis of multiple cancer types and the expression is upregulated in various cancers." (PMID 36890610, 2023). "The dysfunction of myc-related zinc finger protein (MAZ) has been proven to contribute to tumorigenesis and development of multiple cancer types." (PMID 34183010, 2021). "MAZ is upregulated in many types of cancers and is widely involved in the occurrence, development and metastasis of tumors." (PMID 34183010, 2021). "In cancers, MAZ is generally highly expressed in a variety of human tumors, which further promotes the development, progression, and metastasis of cancer by transcriptionally activating multiple downstream target genes." (PMID 31488180, 2019). "Myc-associated zinc-finger protein (MAZ) is a well-documented oncogene involved in the progression and metastasis of multiple cancer types, even in PCa." (PMID 31488180, 2019). "The top-ranked miRNAs (mir-199, mir-29, mir-200) and transcription factors (FOXO4, E2A, NFAT, and MAZ) were identified, which play an important role in deregulating cellular energetics; and regulating angiogenesis and cancer immune system." (PMID 29348878, 2017). "MAZ, a transcriptional factor related to the development and progression of a variety of cancers, is highly expressed in PCa tissue and cell lines." (PMID 27768596, 2016). "SAF-1 and its human homolog, myc-associated zinc finger protein (MAZ) 15 have been shown to be overexpressed in many human cancers 14,16–19." (PMID 25449683, 2015). "This suggests that MAZ probably contributes to regulation of apoptosis mostly through its mediation of PPARγ1 signaling in cancer cells." (PMID 19061500, 2008). "This was anticipated since we believe transcription factors other than MAZ are involved in regulation of PPARγ1 in cancer cells." (PMID 19061500, 2008). "As previously reported, MAZ was a cancer‐promoting gene in many malignant tumors." (PMID 40411278, 2025). "MAZ are overexpressed in cancers and promotes cancer development and metastasis." (PMID 38316778, 2024). "MAZ was reported to be upregulated in ccRCC, and upregulated MAZ promotes cancer." (PMID 36890610, 2023). "MAZ, a critical driver of inflammation in animal models, is abnormally expressed in cancers." (PMID 36988258, 2023).